ENSG00000274276 (cystathionine-beta-synthase like)
Synonyms: CBSL; LOC102724560
Gene: Gene (Ensembl biotype artifact) on chromosome 21 (6,444,869 to 6,467,513, reverse strand). Ensembl gene ENSG00000274276.
Diseases named in the same sentence as ENSG00000274276 in open-access papers:
ENSG00000274276 is named in the same sentence as 3 diseases in open-access papers, as found by Europe PMC text mining. Sharing a sentence is not in itself a finding about the gene and the disease.
ENSG00000274276 shares sentences with these, for which no sentence is quoted: diabetes (1 paper); infection (1); lung carcinoma (1).